PCNA (proliferating cell nuclear antigen)
Diseases named in the same sentence as PCNA in open-access papers (continued):
Sharing a sentence is not in itself a finding about the gene and the disease.
cancer (continued). "PCNA1 (Proliferating Cell Nuclear Antigen) is an auxiliary protein for DNA polymerase that is highly expressed during the S phase of the cell cycle and is widely used as an index of the proliferative cell activity in cancer tissues and plant cells." (PMID 33995437, 2021). "In addition, the expression of WTAP was positively correlated with the expression of the cancer proliferation markers Ki-67 and proliferating cell nuclear antigen (PCNA) in the HCC samples." (PMID 33937023, 2021). "The mechanism may be through the reduction of Ki67 and PCNA levels and inhibition of proliferation of cancer cells; The Caspase-3 and Caspase-9 promote the apoptosis of cancer cells; thereby inhibiting the ability of cancer cell invasion." (PMID 34482792, 2021). "The status of PELP1 immunoreactivity in LUAD was significantly higher than that in the NTL tissues and significantly positively correlated with less differentiated features of carcinoma cells, positive lymph node metastasis, higher clinical stage as well as the status of ERα, ERβ, and PCNA." (PMID 34257530, 2021). "Our recent discovery that IGF1R could increase cellular tolerance to DNA replication stress by direct phosphorylation of PCNA in stem cells prompted us to investigate this mechanism in cancer cells." (PMID 32701997, 2020). "This was assessed by staining matrices containing cancer cells and PSCs for PCNA." (PMID 32203220, 2020). "The study of the post-translational modifications of PCNA and its partners may yield therapeutic opportunities in cancer treatment, in addition to illuminating the way PCNA coordinates the dynamic exchange of its many partners in DNA replication and repair." (PMID 32276417, 2020). "Moreover, the upregulation of HMGB1 and PCNA promotes the proliferation and migration of cancer cells." (PMID 32754037, 2020). "It has been reported that PCNA was a typical biological marker of cancer cell proliferation." (PMID 33062725, 2020). "PCNA has proven to be a useful marker for cancer cell proliferation and prognostic evaluation." (PMID 32429354, 2020). "DNA fiber analysis revealed that IGF1R activation could rescue stalled DNA replication forks, but only in cancer cells with baseline IGF1R/PCNA interaction." (PMID 32701997, 2020). "Interestingly, RAD18 promotes replication fork protection in BRCA1 mutant cancers through the PCNA-TLS pathway." (PMID 32182354, 2020). "In conclusion, our hypothesis-driven focus to target DNA repair gene expression adjusted for the PCNA metagene as a means of predicting OS in various cancers resulted in statistically significant sets of DNA repair genes." (PMID 30965671, 2019). "Furthermore, miR-497-5p was negatively correlated with the expression of cancer marker PCNA in GC patients based on the TCGA database." (PMID 31409724, 2019). "Besides, to clarify the proapoptosis effect of QE in cancer tissues, we measured the expression of PCNA and Bax using western blot." (PMID 31273958, 2019). "Additionally, to clarify the function of extracellular NAMPT in cancer cell proliferation, we conducted an immunohistochemical analysis of PCNA and intracellular and extracellular NAMPT, which showed consistent results." (PMID 31817697, 2019). "Statistical randomization test results indicate that after PCNA adjustment, OS could be predicted significantly by sets of DNA repair genes for 61% (11/18) of the cancers." (PMID 30965671, 2019). "Great efforts have been made to develop novel approaches targeting PCNA for cancer therapy." (PMID 31600334, 2019). "Our results are supportive of cytosolic roles of PCNA, and suggest that targeting PCNA could be a novel strategy to increase anti-cancer efficacy of targeted therapies." (PMID 31921382, 2019).
cancer (continued). "If the hypothesis is correct than this is a unique mechanism for inhibition of PCNA dependent functions and has potential for future anti-cancer therapy." (PMID 30406112, 2018). "Because of its role in proliferation, PCNA is a target for cancer therapy." (PMID 30107825, 2018). "Therefore, CPP-pep8-mediated blocking of exosomal PCNA interaction with NK cells can also lead to increase in NK activity against cancer cells." (PMID 29875773, 2018). "PCNA is an attractive target for cancer therapy and PCNA levels are increased in some cancer cells." (PMID 30126151, 2018). "The accumulating evidences of PCNA expression on the membrane of cancer cell line and cancer stem cells, and the interaction of PCNA with NKp44 and HLA class I or II, open the possibility of the existence of PCNA as an immune regulatory protein in the extracellular level." (PMID 29875773, 2018). "Furthermore, tumors derived from co-implantation of cancer cells and fibroblasts had increased numbers of PCNA-positive cancer cells, suggesting that increased tumor volume was partly due to increased cancer cell proliferation." (PMID 30108679, 2018). "We investigated whether an increased anti-cancer effect could be observed in vivo in the TRAMP model of PCa by combining docetaxel with the PCNA targeting APIM-peptide." (PMID 29545934, 2018). "Since NKp44 interact with PCNA, we hypothesized that NKp44-derived linear peptides could specifically bind PCNA and lead to inhibition of cancer cell proliferation and/or lead to cell death." (PMID 29875773, 2018). "In addition, compounds that inhibit formation of the PCNA trimer by docking at the monomer interface of the PCNA and a peptide that prevents phosphorylation of the PCNA Y211 inhibited cancer growth." (PMID 29651420, 2018). "Targeting PCNA via peptides was shown to have a profound impact on cancer cells growth." (PMID 29875773, 2018). "One study demonstrated the binding of PCNA to cytoplasmic and membrane proteins, indicating that the interaction may be required in cancer migration." (PMID 29642589, 2018). "PCNA expression is upregulated in cancer cells relative to healthy normal cells and can be used as a marker of cell proliferation and cancer virulence in many types of cancers." (PMID 29875773, 2018). "Since overexpression of PCNA is prevalent in malignant tumors, our study provides insight from view of DNA repair that PCNA may be used as target of chemotherapy." (PMID 28116145, 2017). "However, UHRF1 overexpression is a better diagnosis and prognostic biomarker in cancers as compared with Ki67 and PCNA since it fulfills the requirement of an independent factor." (PMID 28881702, 2017). "Importantly, in this group of cancer patients, CA125 and PCNA (conventional markers) were associated with poor overall survival, as would be expected." (PMID 28978006, 2017). "The expression of PCNA was significantly up-regulated in cancer tissues when compared with their matched normal ones that may reveal its roles of potential biomarker." (PMID 28165029, 2017). "Indeed we showed PCNA over expression in cancer for the current study by comparing PCNA expression in matched normal and cancer tissue (TCGA data)." (PMID 27765926, 2016). "In addition, proliferating cell nuclear antigen (PCNA) staining was applied to assess cancer cell proliferation." (PMID 27153561, 2016). "PCNA is used as a prognostic marker of cell proliferation in cancer transformations." (PMID 27448980, 2016). "Importantly, it is clear that the involvement of PCNA in cell cycle and proliferation is much more influential in promoting cancer virulence than its effect on immune suppression." (PMID 27102296, 2016).
cancer (continued). "In addition, SET8 catalyzes monomethylation of proliferating cell nuclear antigen (PCNA) that results stabilization of PCNA protein and consequentially promotes cancer cell proliferation." (PMID 26258118, 2015). "PCNA protein is an indicator for presence of different cancers." (PMID 26201720, 2015). "Overall, the information gathered in this study has led to the identification of SAR-24, which is denoted as PCNA-I1S for its superior potencies and potentially improved solubility, and will be used for future development of PCNA-targeting cancer therapy studies." (PMID 25729582, 2015). "PCNA is a member of the DNA sliding clamp family of proteins that assists in DNA replication and repair, and considered to be a marker of cell proliferation in various cancers." (PMID 25884313, 2015). "However, the fact that PCNA is also expressed in normal squamous epithelium precludes the use of this marker as a potential screening tool for this cancer." (PMID 26308848, 2015). "Immunohistochemical analysis revealed that cancer cell growth (proliferation), as reflected by the expression of PCNA, was significantly lower in the tumors from the mice treated with TPA + DDTC than in the tumors from the mice treated with either TPA or DDTC alone." (PMID 25847449, 2015). "The exact mechanisms of DNMT upregulation remain unclear, but it is suggested that aberrant DNMT activity, especially with regard to DNMT1, is due to a rapid proliferation of cancer cells because DNMT1 binds to proliferating cell nuclear antigen (PCNA)." (PMID 25197641, 2014). "To explore the mechanism by which R9-caPep kills cancer cells, we first examined whether the caPeptide (caPep) interferes with PCNA interaction in vitro by SPR (see Materials and Method for details)." (PMID 24728180, 2014). "PCNA (proliferating cell nuclear antigen) acts as an antigen expression in the cell nuclei in the phase of DNA synthesis during cell cycle and considers the cancer prognosis, but the relationship to IP is still controversial." (PMID 25013792, 2014). "To determine the cytotoxic potential of blocking protein-protein interaction involving the L126-Y133 region of PCNA in cancer cells, we generated the R9-caPep by fusing the L126-Y133 sequence of PCNA to the C-terminus of a nine D-arginine sequence (R9) through a spacer of two cysteines." (PMID 24728180, 2014). "Mechanistically, R9-caPep is able to selectively block PCNA interactions in cancer cells." (PMID 24728180, 2014). "Mechanistically, the peptide is able to block PCNA interactions in cancer cells." (PMID 24728180, 2014). "Collectively, these observations support the hypothesis that the R9-caPep exerts its effect on cancer cells at least partly by interfering with DNA replication through blocking PCNA interactions with its binding proteins." (PMID 24728180, 2014). "Proliferating cell nuclear antigen (PCNA) was originally identified as an antigen expressed in the nuclei of cells during the DNA synthesis phase of the cell cycle, and only exists in normal proliferative cells and cancer cells." (PMID 23805830, 2013). "In other in vivo studies including α-tocopherol, β-carotene, lycopene, and mixed carotenoids, in which they were used to treat cancer-induced hamsters, these carotenoids acted as suppressors of the cell cycle inhibiting the expressions of proliferating cell nuclear antigen (PCNA) and cyclin D1." (PMID 24135910, 2013). "Additionally, PCNA was found to be an inhibitor of natural cytotoxicity receptor NKp44 and to promote immune evasion of cancer cells." (PMID 23936203, 2013).
cancer (continued). "Moreover, at the molecular level, inhibition of Dicer in human cancer U251, MCF-7 and SCG7901 cell lines enhanced the expression of cell cycle-associating molecules cyclin A and PCNA, as well as invasion-promoting factors MMP-2 and MMP-9." (PMID 23599754, 2013). "Protein levels for PCNA dropped by a factor of 0.35 in fibroblasts and 0.31 in cancer cells." (PMID 22321936, 2012). "PCNA labeling index was higher in dysplastic and cancer tissue than that in normal." (PMID 22272378, 2012). "PCNA labeling index of dysplasia and cancer (75 ± 5) was higher than that of control (30 ± 5)." (PMID 22272378, 2012). "We have previously used cancer cell lines to demonstrate PCNA polyubiquitination." (PMID 20353596, 2010). "However, in a previous study we were the first to demonstrate that K63-linked polyubiquitination is important in human fibroblasts and that PCNA is both mono and polyubiquitinated in cancer cell lines by Rad18 and Ubc13." (PMID 20353596, 2010). "Furthermore, recurrent cancer cells expressed Ki-67 and PCNA at a lower level than the primary lesion in each specimen." (PMID 21092332, 2010). "PCNA-labeling indices of tumors from mice treated with the control diet were significantly higher than tumors from mice on the fish oil diet, suggesting that there was a decrease of cancer cell proliferation in the fish oil diet group." (PMID 20421971, 2010). "Expression of proliferating cell nuclear antigen (PCNA) is increased in several types of cancers." (PMID 21203518, 2010). "Changes in PCNA expression, however, may be difficult to detect in cancer cell lines like SEG-1 because they are already selected for optimal growth in culture." (PMID 17597535, 2007). "Studies have shown that the combination of APIM-peptide and cisplatin alters the expression of proteins involved in cancer cell growth and cisplatin resistance, reduces the expression of genes related to the DNA damage response, and likely inhibits key pathways dependent on PCNA interactions." (PMID 41024300, 2025). "Since PCNA and its partners playsprominent roles in DNA replication, repair, and cell cycle progressionevident in the enrichment data, the integrated upregulation of these genes implies amplified proliferativeactivity and genomic instability in cancer development." (PMID 40657100, 2025). "Thus, based on our results showing that the PCNA mRNA level decreased at higher maca doses, potential uncontrolled cancer cell proliferation could also be limited." (PMID 40005158, 2025). "AOH1996 is lethal to malignant tumors but not normal cells and inhibits cancer-associated PCNA." (PMID 41024256, 2025). "Given the growing interest in oncolytic viruses (OVs) as a novel cancer therapeutic, this review considers the role of PCNA in healthy, cancerous, and immune cells to gain an understanding of how PCNA targeted therapy and oncolytic virotherapy may interact in the future." (PMID 39205238, 2024). "Moreover, our data highlight that RAD18 is required for PCNA monoubiquitination upon HU treatment as detected by immunoblotting, consistent with our finding that PCNA ubiquitination at the K164 residue promotes fork recovery in BRCA1-deficient cancer cells." (PMID 38943334, 2024). "Moreover, in WI-38 normal fibroblasts, HeLa, and A431 cancer cells, Aurora B kinase was localized to the nucleus during the S phase and formed foci partially co-localized, or at least in very close proximity to PCNA." (PMID 39513910, 2024). "Additionally, previous studies reported that ESCC-associated proteins, including PCNA, SLC7A5, CTTN, RB1, EGFR, TP63, and PRMT1, exhibited increased expression in S-III; among these proteins, SLC7A5 and EGFR were FDA-approved drug targets for cancer treatment." (PMID 38652547, 2024).
cancer (continued). "Altogether the results presented herein supports that PCNA can serve as a scaffold in glycolytic metabolons and shows that targeting PCNA and its regulatory roles during cellular stress may be highly relevant for cancer treatment." (PMID 36564470, 2023). "This difference may be attributable to differences in the nuclear-to-cytoplasmic relocalization of PCNA, as reported in neutrophils, or the variable expression of Annexin A2, a membrane that traffics protein to lipid rafts, as reported in other cancers." (PMID 37686697, 2023). "The subsequent interaction of the cell surface PCNA (csPCNA) with NKp44 initiates a potent signaling cascade that is predominantly mediated by immune receptor tyrosine-based inhibitory motifs (ITIMs), which inhibit the killing activity of NK cells against cancer cells." (PMID 37686697, 2023). "Targeting this regulatory role of PCNA may be exploited in cancer therapy." (PMID 36564470, 2023). "Our results demonstrated that the wild-type PyMT cancer cells expressed dramatically higher levels of the mesenchymal molecules than the 211F cells, supporting the essential function of Y211 phosphorylation in PCNA in driving a desmoplastic environment to facilitate invasion." (PMID 35628489, 2022). "PCNA expression has been used as a potential marker for the proliferative activity of the tissues, and it could be used as a biomarker for the diagnosis and prognosis of different malignant tumors." (PMID 36297408, 2022). "PCNA, an ideal cell proliferation indicator, is an intranuclear polypeptide synthesized or expressed in various stages of the cell cycle, such as G1, G2, and S phases, and its expression intensity can accurately predict the proliferative activity and malignancy of various cancer cells." (PMID 35911648, 2022). "Furthermore, PCNA-stained sections were evaluated to confirm the anti-cancer efficiency of SsD." (PMID 33897884, 2021). "Therefore, targeting PCNA is a promising strategy for suppressing cancer cell proliferation." (PMID 33802602, 2021). "These peptides/proteins serve a pivotal role in modulating the energy biometabolism of tumors, the transformation of cancer cells from the epithelium to the stroma, the stableness of the c-myc oncoprotein, as well as the ubiquitination and degeneration of proliferating cell nuclear antigen (PCNA)." (PMID 33718157, 2021). "In addition to the regulation of AKT and MAPK signaling, which could directly or indirectly impact various aspects of cell metabolism, recent studies indicate that the IGF-1R can directly interact with and phosphorylate PCNA in some cancer cell lines." (PMID 33753168, 2021). "Finally, we investigated the function of the IGF1R/PCNA interaction in several cancer cell lines." (PMID 32701997, 2020). "Thus, targeting PCNA with PCNA-I1S may provide a novel approach for enhancing the efficacy of DNA damaging chemotherapy and radiation therapy in treatment of cancer." (PMID 31600334, 2019). "Interestingly, using the expression of PCNA and CCND1, two hallmark cell-cycle genes, as a proxy for proliferation status, we did not observe a significant difference between high- and low-proliferating cancer cells." (PMID 31501864, 2019). "Recently, it has become evident that PCNA also functions as a scaffold outside the nucleus and is important for regulation of vital cellular mechanisms such as apoptosis, immune invasion in cancer cells, glycolysis, and cellular signaling involving the PI3K/Akt/mTOR and MAPK pathways." (PMID 29545934, 2018). "Thus, it is possible that mono-ubiquitinated PCNA could be a drug target for chemo-sensitization with cancer therapeutics." (PMID 30406112, 2018). "Therefore, PCNA is a target for the development of anti-proliferation and anti-cancer drugs." (PMID 30406112, 2018).